OGT (O-linked N-acetylglucosamine (GlcNAc) transferase)
Diseases named in the same sentence as OGT in open-access papers (continued):
Sharing a sentence is not in itself a finding about the gene and the disease.
hepatocellular carcinoma (continued). "OGT activated stem‐like cell potential of hepatoma cell through O‐GlcNAcylation of eukaryotic initiation factor 4E." (PMID 30677218, 2019). "Our evidence that endogenous lamin A is O-GlcNAcylated in human hepatoma cells and mouse liver demonstrates biological OGT targeting of lamin A in liver." (PMID 29772801, 2018). "For example, liver‐specific OGT deletion perturbs metabolic homeostasis and alters the expression of core autophagy proteins, linking systemic O‐GlcNAc flux to stress‐adaptive autophagy in a setting relevant to hepatocellular carcinoma." (PMID 41540817, 2026). "The deubiquitinase EIF3H promotes hepatocellular carcinoma progression by stabilizing OGT." (PMID 39715739, 2024). "O-Linked N-Acetylglucosamine (GlcNAc) Transferase (OGT) was found to promote influenza A virus replication and cytokine production and its overexpression has been linked to hepatitis C virus (HCV) infectivity and HCV-induced hepatocellular carcinoma." (PMID 34746025, 2021). "Importantly, we found that PCK1 inhibits motility of hepatoma cell via downregulating cellular O-GlcNAcylation levels by detecting the cellular motility in response to OGT or OGA inhibition." (PMID 34650217, 2021). "We found that OGT was highly expressed in hepatocellular carcinoma." (PMID 30677218, 2019). "High glucose promoted stem‐like cell potential of hepatoma cell through OGT‐eIF4E axis." (PMID 30677218, 2019). "In this study, we investigated the roles of OGT in hepatoma development." (PMID 30677218, 2019). "We first examined the effect of OGT knockdown on hepatoma cell growth." (PMID 30677218, 2019). "Interestingly, down‐regulation of OGT expression inhibited the tumorsphere formation of hepatoma cell." (PMID 30677218, 2019). "Similar findings have been observed in hepatocellular carcinoma (HCC), highlighting OGT’s crucial role in tumor growth by regulating FBP1." (PMID 39285476, 2024). "This study provides insight into a possible mechanism of chemotherapy resistance, identifies potential novel drug targets, and suggests that OGT inhibition could be utilized in clinical applications to treat hepatocellular carcinoma as well as other cancer types." (PMID 33121131, 2020). "For instance, in hepatocellular carcinoma, USP8 inhibition induces ferroptosis by destabilizing OGT, thereby disrupting SLC7A11-mediated cystine uptake." (PMID 40813720, 2025). "Specifically, in HCC, SPOP is highly O-GlcNAcylated by O-GlcNAc transferase (OGT) at Ser96, which enhances the nuclear localization of SPOP in hepatoma cells." (PMID 40521202, 2025). "Moreover, O-GlcNAc of ZNF263 at Ser 662 promotes its chromatin association with OGT and facilitates its binding to the promoters of genes such as DOCK7, NPTX1, and UFSP2, thereby influencing hepatocellular carcinoma (HCC) progression." (PMID 41280891, 2025). "For instance, OGT enhances the PI3K/AKT/mTOR signaling pathway by modifying fatty acid synthase (FASN), which promotes hepatoma cell proliferation." (PMID 39487556, 2024). "Additionally, OGT plays a critical role in chemoresistance in hepatocellular carcinoma (HCC) and other cancers." (PMID 39487556, 2024). "Expression of OGT, C8orf33, DGKA and SMTN has been correlated with cardiovascular disease, hepatocellular carcinoma, acute myeloid leukemia and hypertension, respectively." (PMID 37026480, 2023). "In hepatoma FAO cells, it was reported that the interaction of OGT with HCF-1, a transcriptional cofactor playing critical roles in cell cycle and stem cell regulation, enhanced the O-GlcNAcylation of transcription factor PGC-1α." (PMID 36291918, 2022). "Similarly, ST045849, an OGT inhibitor, suppresses prostate cancer cell proliferation via metabolic reprogramming, and has been shown to inhibit hepatocellular carcinoma (HCC) cell proliferation." (PMID 33194731, 2020).
hepatocellular carcinoma (continued). "Treatment with OSMI-1, a potent inhibitor of O-GlcNAc transferase (OGT), led to a significant decrease in O-GlcNAcylation levels, suggesting that GFAT1 promotes UDP-GlcNAc biosynthesis and O-GlcNAc modification in hepatoma cells in an enzyme activity-dependent manner." (PMID 40858565, 2025). "OGT-mediated O-GlcNAcylation of YTHDF2 enhanced its protein stability and oncogenic activity by inhibiting YTHDF2 ubiquitination and then promoted HBV-related hepatocellular carcinoma progression in an N6-methyladenosine-dependent manner." (PMID 38575607, 2024). "Upon initial exploration of the relationship between this gene and hepatocellular carcinoma cell (HCC), we observed that YAP, OGT, SLC5A3, and Nudt9 expression in HCC tissues was upregulated relative to that in normal liver tissues through The Cancer Gene Atlas (TCGA) online visualization website." (PMID 34588426, 2021). "Herein, we investigated doxorubicin (DOX) and O-GlcNAc transferase (OGT) inhibitor OSMI-1 combination treatment, which significantly enhanced apoptosis in hepatocellular carcinoma cells (HepG2) as a result of synergistic drug action in disparate stress signaling pathways." (PMID 33121131, 2020). "For instance, APS impeded O-GlcNAc synthesis by decreasing OGT and augmenting OGA levels in doxorubicin (Dox)-treated Hep3B hepatocellular carcinoma (HCC) cell, leading to exacerbated Dox-induced ER stress, as evidenced by elevated CHOP expression." (PMID 41155562, 2025). "Moreover, sWGA pull-down assays in hepatoma cells and HEK293 cells indicated that HBV infection or TMG treatment significantly enhanced total O-GlcNAcylation and YTHDF2 O-GlcNAcylation, whereas the OGT inhibitor OSMI-1 downregulated both processes." (PMID 36765030, 2023). "Inhibition of USP8, by stabilizing OGT and impacting cystine uptake via SLC7A11, effectively suppresses hepatocellular carcinoma progression and induces ferroptosis, suggesting its potential as a therapeutic target for HCC treatment." (PMID 39315094, 2024). "A recent report revealed that treating hepatocellular carcinoma cells with a ferroptosis inducer (e.g., erastin or RSL3) increases OGT activity, while not affecting OGT abundance or UDP-GlcNAc levels." (PMID 41005476, 2025).
prostate carcinoma (32 papers, 2013 to 2025). A carcinoma that arises from epithelial cells of the prostate gland. "A study using cDNA microarray analysis also showed that the gene encoding OGA is markedly down-regulated by silencing of OGT expression in prostate cancer cell lines." (PMID 33801653, 2021). "OGT is upregulated in primary prostate cancer, and this is linked to a higher Gleason score, reduced time to biochemical recurrence, and increased c-Myc stability." (PMID 30893936, 2019). "OGT overexpression was associated with prostate cancer progression and recurrence, and high O-GlcNAc IHC staining was an independent prognostic factor for poor survival." (PMID 30123425, 2018). "O-linked glycosylation was recently shown to be elevated in prostate cancer and OGT itself was shown to regulate invasion and angiogenesis." (PMID 23724116, 2013). "Furthermore, high OGT expression is associated with poor disease-free survival after treatment with prostate cancer." (PMID 33535386, 2021). "Importantly, the inhibition of OGT has been associated with decreased proliferation of breast and prostate cancer cells." (PMID 27703839, 2016). "In prostate cancer biopsies, OGT is upregulated in association with MYC levels." (PMID 23964270, 2013). "Similarly, the same group showed that inhibition of OGT in the prostate cancer cell line PC3-ML was associated with an increase in FOXM1 degradation through a proteasome-mediated process." (PMID 23964270, 2013). "Furthermore, OGT knockdown in prostate cancer cell lines was associated with reduced expression of MMP-2, MMP-9, and vascular endothelial growth factor (VEGF), thereby inhibiting invasion and angiogenesis through the regulation of the oncogenic transcription factor forkhead box M1 (FoxM1)." (PMID 39285476, 2024). "Previous studies have shown that OGT inhibition with OSMI‐1, an OGT inhibitor, increases sensitivity to the anticancer drug doxorubicin in HepG2 human liver cancer cells and PC‐3 prostate cancer cells." (PMID 40237201, 2025). "For example, studies have shown that OGT inhibition reduces cell cycle progression in a cMYC‐dependent manner in prostate cancer cells and decreases epithelial–mesenchymal transition, metastasis, and invasion in vivo." (PMID 40237201, 2025). "O-GlcNAcylation has a dominant effect on cancer metabolism; for example, OGT inhibition reduces glucose uptake and lactate production, thus suppressing the proliferation of prostate cancer cells." (PMID 39178944, 2024). "In prostate cancer, OGT ablation reduces the expression of angiogenic factors, such as vascular endothelial growth factor, matrix metallopeptidase 2 (MMP2), and MMP9, to block angiogenesis." (PMID 39178944, 2024). "In prostate cancer, genetic and pharmacological inhibitions of OGT sensitize the cells to apoptosis induced by docetaxel, an anti-cancer drug that inhibits depolymerization of microtubules and cell division." (PMID 37838167, 2023). "Inhibition of OGT in prostate cancer cells also remarkably reduces metastasis incidents in mice models." (PMID 37838167, 2023). "In prostate cancer, combined treatment using Cdk9 inhibitor and OGT inhibitor is selectively effective in inducing apoptosis." (PMID 37838167, 2023). "OGT is overexpressed in prostate cancer patients, and the enzyme is enriched in the transcriptionally active chromatin in the prostate cancer cells." (PMID 36401094, 2023). "This implies that prostate cancer cells mount an adaptive response that enables their survival despite the diminished OGT activity." (PMID 35708495, 2022). "To test if OGT regulates MRE11 chromatin-association, we isolated nuclear/cytosolic- and chromatin-fractions from prostate cancer cells treated with CDK9 inhibitor in the presence and absence of the OGT inhibitor OSMI-4." (PMID 35164752, 2022). "The combinatorial lethality was observed in prostate cancer cells treated with an OGT inhibitor (OSMI-2) and a CDK9 inhibitor (AT7519)." (PMID 35708495, 2022).
prostate carcinoma (continued). "Both the PCA analysis and more detailed mapping of the metabolic profiles show that the metabolic dynamics are governed by OGT in prostate cancer cells." (PMID 35708495, 2022). "Among them, OSMI-2 acts as a rapid-acting OGT inhibitor in combination with anti-androgens to target MYC-dependent prostate cancer cells." (PMID 36104770, 2022). "Accordingly, we show that combined inhibition of CDK9 and either OGT or MRE11 induces robust DNA damage in prostate cancer cells." (PMID 35164752, 2022). "Compounds targeting OGT have minimal effects on the proliferation rate of prostate cancer cells but have profound effects on the mitochondrial activity of these cells." (PMID 35708495, 2022). "In conclusion, we have shown that OGT is required for the pro-survival metabolic rewiring of prostate cancer cells treated with CDK9 inhibitor." (PMID 35708495, 2022). "We have shown that O-GlcNAc transferase (OGT) is overexpressed in prostate cancer, making this enzyme a potential drug target for the disease." (PMID 35708495, 2022). "The expression of O-GlcNAc transferase (OGT) and its catalytic product, O-GlcNAcylation (O-GlcNAc), are elevated in many types of cancers, including prostate cancer (PC)." (PMID 36439421, 2022). "We have shown that OGT is overexpressed in aggressive prostate cancer, and we also discovered that OGT becomes a point of vulnerability during androgen-ablation." (PMID 35164752, 2022). "More in-depth research results confirmed the correlation between the OGT protein level and tumor metastatic progression in prostate cancer cells." (PMID 33194731, 2020). "They found that reducing O-GlcNAc by shRNA inhibition of OGT in prostate cancer cells led to increased FoxM1 protein degradation." (PMID 31466420, 2019). "More importantly, OGT inhibition in prostate cancer cells decreased angiogenesis when overlaid on HUVEC cells." (PMID 31466420, 2019). "Many studies have revealed an increased level of OGT or protein O-GlcNAc in high-grade breast, colon, and prostate cancer when compared to low-grade ones." (PMID 31466420, 2019). "In cancer cells, O-GlcNAcylation and OGT play important roles in glucose metabolism as targeting OGT in breast or prostate cancer cells reduces glucose consumption and lactate production and is associated with reduced growth." (PMID 31272438, 2019). "Inhibition of OGT expression has been shown to decrease the viability and invasion of prostate cancer cells through reduction of transcription factor FoxM1." (PMID 26824323, 2016). "In this study, we used ST045849, a commercially available inhibitor, to study the effect of OGT inhibition on prostate cancer cell viability and metabolic reprogramming." (PMID 26824323, 2016). "Having established that glucose consumption is significantly decreased in prostate cancer cells treated with OGT inhibitor ST045849, we moved on to evaluate the levels of intracellular metabolites." (PMID 26824323, 2016). "Additional studies have observed that reduction of OGT expression in prostate cancer cells inhibits metastatic tumor progression to bone." (PMID 27703839, 2016). "It appears that decrease OGT activity can disrupt this positive cell cycle promoting regulatory relationship in prostate cancer cells and it remains to be determined if same is true in other cancers." (PMID 26824323, 2016). "In this study, we treated prostate cancer cells with a commercially available OGT inhibitor ST045849 and analysed samples with 1H Nuclear Magnetic Resonance (NMR) spectroscopy." (PMID 26824323, 2016). "In this work, we have defined complementary inhibitor targets, oxidative phosphorylation and GPT2, which can enhance response to OGT inhibition in prostate cancer cells." (PMID 26824323, 2016). "Combining OGT inhibition with GPT2 inhibition induced cell death specifically in prostate cancer cells." (PMID 26824323, 2016).
prostate carcinoma (continued). "As expected, and based on previous studies, OGT inhibitor ST045849 significantly inhibited the viability of prostate cancer cells." (PMID 26824323, 2016). "Taken together, here we report the reprogramming of energy metabolism upon inhibition of OGT activity, and identify synergistically lethal combinations that are prostate cancer cell specific." (PMID 26824323, 2016). "The authors observed that RNA interference-mediated silencing or pharmacologic inhibition of OGT correlated with prostate cancer cell growth." (PMID 25315705, 2015). "The OGT levels were also analyzed as prognostic factors and it was observed that disease-free survival 5 years post-treatment for prostate cancer was higher in patients with a low OGT expression profile compared with patients with increased OGT expression." (PMID 24918087, 2014). "Additionally, OGT inhibitors exhibit potential in combination chemotherapy by increasing the sensitivity of prostate cancer cells to docetaxel and enhancing the efficacy of chemotherapy." (PMID 39358921, 2024). "Likewise, treatment with docetaxel upregulates miR-140 expression in prostate cancer cells, and miR-140 can directly bind to the 3′-untranslated region of OGT mRNA to suppress its expression, thereby enhancing the drug sensitivity of PC cells to docetaxel." (PMID 39487556, 2024). "Knockdown of OGT sensitizes prostate cancer cells to docetaxel." (PMID 39285476, 2024). "Additionally, OGT O-GlcNAcylates Bmi-1 at Ser255, thus inhibiting apoptosis in prostate cancer cells." (PMID 39285476, 2024). "In prostate cancer, inhibition of OGT results in the depletion of intracellular alanine." (PMID 37838167, 2023). "The same synergetic effect of OGT inhibitor and doxorubicin is also observed in prostate cancer." (PMID 37838167, 2023). "Indeed, combined treatment of prostate cancer cells with OGT inhibitor and the CDK9 inhibitor NVP2 induced the accumulation of p-H2AX in PC and CRPC cells but not in the normal prostate cells." (PMID 35164752, 2022). "In our experiments, we noted that co-treatment of prostate cancer cells with vitamin B5 and CDK9 inhibitor induces combinatorial antiproliferative effects and further increased DNA damage, which were associated with decreased OGT expression." (PMID 35708495, 2022). "We found that OGT can be used as a target to enhance the sensitivity of prostate cancer cells to chemotherapy drugs, which might also play a role in drug resistance of PC cells." (PMID 36439421, 2022). "Inhibition of CDK9 results in an OGT-dependent remodeling of the proteome in prostate cancer cells." (PMID 35164752, 2022). "Finally, supplementing prostate cancer cell lines with vitamin B5 in the presence of CDK9 inhibitor mimics the effects of co-targeting OGT and CDK9." (PMID 35708495, 2022). "Other groups showed that OGT expression is involved in prostate cancer metastasis." (PMID 33535386, 2021). "Targets OGT, and suppresses proliferation of prostate cancer and HCC." (PMID 33194731, 2020). "Inhibits OGT activity, promoting proliferation of prostate cancer." (PMID 33194731, 2020). "Given the established metabolic re-programming of prostate cancer cells, we hypothesised that inhibition of OGT activity might be able to distort cancer cell metabolism." (PMID 26824323, 2016). "Both OGT inhibitors sensitized another prostate cancer cell line, VCaP, to cyclo-serine." (PMID 26824323, 2016). "We show that inhibition of OGT activity inhibits the proliferation of prostate cancer cells, leads to sustained loss of c-MYC and suppresses the expression of CDK1, elevated expression of which predicts prostate cancer recurrence (p=0.00179)." (PMID 26824323, 2016). "We next performed metabolic profiling of prostate cancer cells after OGT inhibitor treatment." (PMID 26824323, 2016). "In addition, OGT inhibition sensitized a third prostate cancer cell line (PC3) to GPT2 inhibition Suppl." (PMID 26824323, 2016).